MMP9 (matrix metallopeptidase 9)
Diseases named in the same sentence as MMP9 in open-access papers (continued):
Sharing a sentence is not in itself a finding about the gene and the disease.
Stroke (continued). "This suggests that reduced neutrophil infiltration may be involved in limiting MMP-9 production, thus resulting in less BBB damage in COX-2−/− mice following stroke." (PMID 32973660, 2020). "Thus, expression levels of HPSE, MMP9, and HYAL1-4 in infarct lesions at 3 and 24 h after stroke onset were investigated using Western blotting." (PMID 33127645, 2020). "MMP-9 plasma concentration is a strong marker of BBB disruption and permeability in stroke." (PMID 33362697, 2020). "Decreased level of MMP-9 in the periphery and CNS could be one important mechanism in closing the BBB by BR therapy for stroke." (PMID 32843630, 2020). "MMP-9, a member belonging to the family of matrix metalloproteinases (MMPs), has been suggested to be involved in the BBB breakdown in neurological disorders, including stroke." (PMID 30705764, 2019). "Valproic acid and sodium butyrate (class I, IIa and III inhibitor) repressed the nuclear translocation of NFκB subunit p65, mitigate MMP9 activity and restore the BBB integrity after stroke by regulating the expression of tight junction proteins, claudin-5, and ZO-1." (PMID 31543756, 2019). "Quantification of the MMP-2 and MMP-9 bands shows increased activity of MMP-9 in stroke patients compared to non-stroke (P < 0.05 in non-stroke vs PI and non-stroke vs R)." (PMID 28290150, 2018). "The upregulation of MMP-9 was an early response of stroke; however, we still do not fully understand the impact of MMP-9 on BBB recovery and how the BBB recovers." (PMID 29551991, 2018). "By employing an angiogenic ELISA assay and Western blot analysis, we also confirmed that APX3330 treatment significantly decreases the expression of inflammatory factors such as MCP1, MMP9 and RAGE and pro-thrombotic factor PAI-1, in the ischemic brain of T1DM stroke rats." (PMID 29896433, 2018). "In this study, we found that APX3330 significantly decreases PAI-1, MCP-1, MMP9 and RAGE levels in the ischemic brain which may contribute to APX3330 induced neuroprotective and neurorestorative effects in T1DM stroke rats." (PMID 29896433, 2018). "Inhibitors of MMP-9 can significantly reduce cerebral edema and BBB disruption in stroke." (PMID 30618576, 2018). "Compared to PBS treatment, APX3330 treatment significantly decreases plasminogen activator inhibitor type-1 (PAI-1), monocyte chemotactic protein-1 and matrix metalloproteinase 9 (MMP9) and receptor for advanced glycation endproducts expression in the ischemic brain of T1DM stroke rats." (PMID 29896433, 2018). "Matrix metalloproteinase-9 (MMP9) is the best-characterized MMP family member and is thought to have an important role in the pathophysiology of neuropsychiatric disorders, such as schizophrenia, bipolar disorder, stroke, neurodegeneration and brain tumors." (PMID 30619470, 2018). "In humans with stroke and in rodent models of stroke, the SUR1 inhibitor, glibenclamide, has been found to reduce hemorrhagic transformation and plasma levels of MMP-9, but the mechanism is unknown." (PMID 29617457, 2018). "The accumulating data revealed that MMPs are deleterious in stroke, in particular MMP-2 and MMP-9." (PMID 28912713, 2017). "MMP-9 expression correlated with stroke severity and poor outcome, as assessed by the NIHSS at 48 h post-stroke but was shown to correlate with NIHSS score early as 24 h post-stroke onset." (PMID 26973468, 2016). "Interestingly, active forms of MMP have been associated with the development of vasogenic edema and disruption of blood vessel integrity in stroke reperfusion therapy and S1PR2 has recently been shown to be critical in MMP-9 activation." (PMID 26884643, 2016). "Information regarding the relationship between MMP-9 and neutrophils may facilitate understanding of the mechanisms involved in BBB breakdown following stroke and ultimately guide therapeutic intervention." (PMID 26973468, 2016).
Stroke (continued). "Certainly MMP-9 has been the most widely studied MMP family member in both the experimental and clinical stroke literature, which may in part be due to the fact that it can easily be assessed using techniques such as gelatin zymography." (PMID 26973468, 2016). "Furthermore, in an OGD model of stroke with primary rat cortical neurons, increased intranuclear location of gelatinase activity and elevated levels of both MMP-2 and MMP-9 of nuclear extracts are detected." (PMID 26925194, 2016). "In contrast, a few studies have reported that neutrophils are not the cellular source of MMP-9 following stroke." (PMID 26973468, 2016). "Although a subsequent study by Montaner showed that high MMP-9 levels correlated with NIHSS score at admission this did not identify a specific stroke etiology." (PMID 26973468, 2016). "However, the aim of the present review was to explore the potential relationship between neutrophil-derived MMP-9 and complications such as BBB disruption and HT following stroke to elucidate the cellular source of MMP-9 in ischemic stroke." (PMID 26973468, 2016). "Matrix metalloproteinase-9 (MMP-9, Gelantinase B) has been shown to relate to stroke and the development of aneurysm and may increase risks of intracerebral hemorrhage." (PMID 25932641, 2015). "Therefore, it is proposed that during stroke, the over- or hyper-activation of TRPV4 aggravates the increase of [Ca2+]i, helping to increase the activated MMP-9." (PMID 25914628, 2015). "Elevated MMP-9 level and activity correlates with BBB breakdown after stroke." (PMID 25418536, 2014). "Diabetes upregulates MMP9 expression and activity, which may contribute to increased brain hemorrhage and BBB leakage after stroke." (PMID 24303036, 2013). "The in vivo effects of the increase in MMP-9 may therefore be determined by its activity relative to TIMP-1, as has been suggested for the use of MMP-9 as a clinical biomarker in stroke." (PMID 22507553, 2012). "In accordance to our results, in two studies median levels of MMP-9 were - although not significantly - lower in stroke patients than in controls at 3 days and 2 to 5 days after stroke, respectively." (PMID 23158556, 2012). "Remarkably, MMP-9 levels were not elevated in stroke patients compared with those in controls in our study." (PMID 23158556, 2012). "While several studies showed increased MMP-9 levels in stroke patients compared to controls, few studies did not detect clear differences." (PMID 23158556, 2012). "Thus, our findings suggest that ROCK promotes microvascular damage by upregulating MMP9 and reveal ROCK as a promising therapeutic target for stroke." (PMID 21541054, 2011). "Consistent with previous reports we did not observe the increase in MMP-9 level in vehicle treated animals of either group at 24 hours after stroke compared to sham controls (data not shown)." (PMID 22177314, 2011). "In one recent large nested case-control study, relations of MMP-9 to myocardial infarction and stroke were observed in unadjusted models, but not in multivariable-adjusted ones." (PMID 21283828, 2011). "Indeed, neutrophils contain and degranulate gelatinase granules resulting in release of pro-MMP-9 and MMP-9 within a day after stroke onset." (PMID 21040547, 2010). "The present study further reinforces the contribution of MMPs for stroke recovery by showing that specific MMP-2, but not MMP-9, gene variants influence stroke outcome." (PMID 20222942, 2010). "Shortly after stroke, MMP-2 and MMP-9 have mainly damaging effects for brain tissue." (PMID 20222942, 2010). "Matrix metalloproteinase-9 (MMP-9) which is a member of matrix metalloproteinases family that normally remodel the extracellular matrix, has been shown to play an important role in both animal models of cerebral ischemia and human stroke." (PMID 20514206, 2009).
Stroke (continued). "However, the molecular mechanisms through which MMP-3 inhibition improves stroke outcome independent of downstream MMP-9 and MMP-2 activation remain largely unexplored." (PMID 39000490, 2024). "Studies have failed to confirm that MMP-9 has any beneficial impact in the acute phase of stroke, where it primarily contributes to processes such as blood–brain barrier damage; indeed, it may serve as a prognostic biomarker of poor outcome." (PMID 38891934, 2024). "In addition, we found that MMP3 and MMP9, which have been shown to play an essential role in promoting BBB disruption, were upregulated in the ischemic brains of MG-specific Nrf2 knockdown stroke mice compared to those of control stroke mice." (PMID 39469715, 2024). "SHS may further participate in developing both stroke subtypes by modulating various channel activities and gene expression, such as activating calcium-dependent potassium channels and upregulating matrix metalloproteinase expression (e.g., MMP-2 and MMP-9)." (PMID 38343713, 2024). "Indeed, we found that stroke resulted in increased activity of MMPs—the main enzymes involved in ECM remodelling—which was detected by in situ zymography of CCA plaque sections and validated by gel zymography for MMP2 and MMP9." (PMID 39112714, 2024). "The secondary outcomes are the National Institute of Health Stroke Scale (NIHSS), Brunnstrom staging (BS), modified Ashworth scale (MAS), Modified Barthel Index (MBI), central motor conduction time (CMCT), precursor proteins of mature BDNF (proBDNF), and matrix metalloproteinase-9 (MMP-9) levels." (PMID 37735708, 2023). "However, due to the lack of low-toxicity selective inhibitors, targeting MMP-9 to reduce stroke damage has been proven to be difficult." (PMID 37483355, 2023). "In rat stroke models, derivatives of caffeic acid such as dihydrocaffeic acid and chlorogenic acid, detected in A. borbonica, were able to reduce brain infarct and BBB damage via inhibition of the expression and activities of MMP-2 and MMP-9 in a dose-dependent manner." (PMID 35624723, 2022). "Besides, Treg cells may protect the integrity of BBB by inhibiting the elevation of matrix metallopeptidase-9 (MMP-9) and C-C motif chemokine ligand 2 (CCL2) in stroke." (PMID 36474712, 2022). "Therefore, this study aims to explore whether butylphthalide combined with conventional treatment can change the levels of MMP-9 and VEGF and the National Institutes of Health Stroke Scale (NIHSS) scores of patients with stroke and improve their prognosis." (PMID 34987460, 2021). "Our data show that 3 μg/kg VT treatment significantly decreases inflammatory factor MMP9 expression (p < 0.05), reduces the number of macrophages (ED1, p < 0.05), and decreases the number of apoptotic cells (TUNEL, p < 0.05) in the IBZ after stroke in T1DM rats compared to PBS‐treated control group." (PMID 33346402, 2021). "Previous studies assessing kinetics of MMP-9 in AIS patients whether or not they are treated with IV thrombolysis with heterogeneous delays from the stroke onset have shown an early increase in the first 24 h." (PMID 32582006, 2020). "However, more significant reduction of iNOS and MMP9 induced by PARP-1 inhibition and better neurological functions were found in male MCAO mice, indicating gender differences of PARP-1 inhibitor treatment for stroke." (PMID 32317937, 2020). "Furthermore, there are premises suggesting value of some biomarkers in the diagnosis of specific stroke types, such as cardioembolic stroke (vWF, TNFα), hemorrhagic stroke (GFAP, MMP-9), large- and small-artery disease (IL-6; TNFα), or lacunar stroke (Glu, GABA)." (PMID 31701356, 2020). "Our data indicate that genetic deletion or pharmacological inhibition of COX-2 reduces MMP-9 production in stroke, which reveals for the first time that COX-2 activity may contribute to MMP-9 expression and activation in the ischemic brain, and the resulting BBB damage." (PMID 32973660, 2020).
Stroke (continued). "Considering the well-known negative effects of MMP-9 in the course of stroke, as well as some evidence indicating its positive function, it can be assumed that place of this marker in diagnosis of stroke is still not precisely defined and requires further basic and clinical studies." (PMID 31701356, 2020). "We did not have the data of MMP-9 expression levels in stroke and comparison cohorts." (PMID 29551991, 2018). "In the same vein, JAK3 inhibition with 10 mg/kg decernotinib did not affect stroke-induced upregulation of Ccl2, Cxcl10, and Cxcl1, chemokines important for immune cell trafficking, nor proinflammatory mediators IL-1β, IL-6, Tnfα, Ptgs2, and Mmp-9 that exacerbate stroke damage." (PMID 28790974, 2017). "There are several potential targets in the MMP-9 regulatory pathway for host-directed therapy in CNS-TB, and of note, both specific and broad-based MMP-inhibitors are currently being explored as adjunctive therapy in other CNS-diseases such as autoimmune encephalomyelitis and stroke." (PMID 28173836, 2017). "The Triage Stroke Panel is a rapid, point-of-care fluorescence immunoassay to be used with the Triage MeterPlus for the rapid, quantitative measurement of BNP, fibrin degradation products containing D-dimer, MMP-9 and S-100β in EDTA-anticoagulated whole blood or plasma specimens." (PMID 27247610, 2016). "Furthermore, the MMP-9 response was shown to be bi-phasic, which did not coincide with neutrophil infiltration into the stroke lesion." (PMID 26973468, 2016). "Human stroke genomic biomarker studies have identified a common panel of five genes responding to AIS in the peripheral blood: arginase 1 (ARG1), lymphocyte antigen 96 (LY96), matrix metalloproteinase 9 (MMP9), s100 calcium-binding protein A12 (s100A12), and chemokine CC motif receptor 7 (CCR7)." (PMID 26515089, 2016). "In a study examining human brain samples after a fatal stroke, MMP-9 and TIMP-2 demonstrated higher expression in brain microvessels, prompting the hypothesis of selectively targeting these molecules for “vasculoprotection” following stroke." (PMID 26074872, 2015). "To examine whether the enhanced MMP9 activity in the peri-infarct region might affect the integrity of BBB, we measured the expression of tight-junction protein occludin in this region using immunofluorescence staining at 14 days after stroke." (PMID 26391329, 2015). "Similarly, tPA induced MMP-2 and MMP-9 upregulation has been reported in human cerebral microvascular endothelial cell culture while increased activity and expression of MMP-9 by recombinant tPA have also been described in stroke." (PMID 23977299, 2013). "In addition, excessive MMP-9 activity can exacerbate pathological outcomes such as disruption of BBB, and enhances neuronal apoptosis and degeneration of neurovascular units after trauma and stroke." (PMID 24194849, 2013). "Quantification of total MMP-9 protein from brain homogenates using ELISA revealed a predominant increase in MMP-9 levels at 5 and 24 hours post ischemia reperfusion, with higher MMP-9 levels detected in the stroke hemisphere during a subacute stroke versus and acute stroke." (PMID 22742423, 2012). "However, individual outcomes like TIA or stroke did not consistently correlate with MMP-9 levels." (PMID 40364266, 2025). "Furthermore, the rise of MMP-9 levels during stroke may also lead to secondary neurodegeneration through BBB disruption and secondary tissue injury, resulting in a worsened cognitive outcomes after stroke." (PMID 41542283, 2024). "Additionally, strong evidence exists that MMP-9 may influence the development of depression or bipolar depression among individuals without stroke." (PMID 38891934, 2024). "Moreover, given the fact that stroke represents a rather heterogenous syndrome, a combined panel incorporating BNP, GFAP, RDW, NLR, MMP-9, and AQP4 might represent a promising approach, both in research and in clinical practice, minimizing the effect of any individual biomarker." (PMID 36278689, 2022).
Stroke (continued). "However, the rise of MMP-9 is not specific to ischemic stroke, moreover its concentration is reported to peak at 24 h post stroke, too late for making decisions about thrombolysis, and standardization of MMP-9 measurements and experimental replication are still required." (PMID 33633673, 2021). "Thus, we did not know whether there was an effect of MMP‐9 gene polymorphisms on stroke severity and END risk in other stroke subtypes." (PMID 31012282, 2019). "Age, gender, procedure laterality, previous stroke, presence of contralateral stenosis, prior ipsi- or contralateral surgery, smoking, pre-existing hypertension and diabetes treated with oral antidiabetic medication did not influence the plasma levels of MMP-9 and TIMP-1 at any time points." (PMID 30157791, 2018). "Morroniside could obviously reduceapp:addword:obviously the expression of MMP-2 and MMP-9 in the peri-infarct area compared with vehicle-treated ischemic rats, which gives some evidence that morroniside may protect BBB function after stroke via the suppression of MMPs." (PMID 24979385, 2014). "In contrast to MMP-9 and MMP-2 expression after r-tPA treatment in ischemic stroke, MMP-3 levels dropped post stroke without r-tPA treatment and further decreased following r-tPA treatment." (PMID 39273389, 2024). "The MMX value obtained by combining the results of four different markers (MMP-9, BNP, S100B, and D-dimer) was significantly higher in stroke patients compared to non-stroke patients." (PMID 39001884, 2024). "Low doses of TMS (0.3–3 mg/kg/d) after MCAO in a model of stroke-resistant spontaneously hypertensive rats (SR-SHR) reduced progressive decrease of N-acetylglucosamine oligomer and increase of MMP-9 positive neurons without reducing BP." (PMID 32156050, 2020). "Therefore, measuring the expression of MMP-9 and its endogenous inhibitor, monitoring the dynamic changes of BBB structure after stroke and finding pathways to target the main proteins involved may lead to more effective protection of the BBB and improved therapeutic approaches for stroke." (PMID 23708107, 2013). "In addition, we observed trends (0.05<p-value≤0.09) in increased levels of GDNF, interleukin (IL)-7, MMP-9, lipocalin-2, IL-4, sP-selectin, and myoglobin, and lower levels of CC5a, in children with TBM-related stroke compared to TBM without stroke." (PMID 33930055, 2021). "Interestingly, at this relative late reperfusion time points (24 hrs after stroke onset), MMP-2 appeared to be constitutively expressed at much lower levels compared with MMP-9, and was not affected by ischemia and reperfusion." (PMID 22146586, 2011). "However, inconsistencies were found concerning individual outcomes like TIA or stroke, which may reflect the multifactorial nature of those events post CEA, whose presence may not be exclusively dependent on MMP-9 levels." (PMID 40364266, 2025).